IGHV5-51 (immunoglobulin heavy variable 5-51)
Description:
V region of the variable domain of immunoglobulin heavy chains that participates in the antigen recognition. Immunoglobulins, also known as antibodies, are membrane-bound or secreted glycoproteins produced by B lymphocytes. In the recognition phase of humoral immunity, the membrane-bound immunoglobulins serve as receptors which, upon binding of a specific antigen, trigger the clonal expansion and differentiation of B lymphocytes into immunoglobulins-secreting plasma cells. Secreted immunoglobulins mediate the effector phase of humoral immunity, which results in the elimination of bound antigens. The antigen binding site is formed by the variable domain of one heavy chain, together with that of its associated light chain. Thus, each immunoglobulin has two antigen binding sites with remarkable affinity for a particular antigen. The variable domains are assembled by a process called V-(D)-J rearrangement and can then be subjected to somatic hypermutations which, after exposure to antigen and selection, allow affinity maturation for a particular antigen.
Synonyms: IGHV551; VH
Gene: Immunoglobulin variable (V) gene on chromosome 14 (106,578,744 to 106,579,236, reverse strand). Ensembl gene ENSG00000211966.
Subcellular location: Secreted; Cell membrane
Gene Ontology:
Molecular function: antigen binding
Biological process: immunoglobulin mediated immune response
Cellular component: extracellular region; plasma membrane
Homologues: Orthologues: chimpanzee IGHV5-51 (84% identical), tropical clawed frog XB5734592 (53% identical). Paralogues in human: IGHV5-10-1 (93% identical), IGHV1-3 (60% identical), IGHV1-46 (60% identical), IGHV1-69 (60% identical), IGHV1-69-2 (60% identical), IGHV1-69D (59% identical), IGHV1-2 (58% identical), IGHV1-18 (57% identical), IGHV1OR15-1 (57% identical), IGHV1-24 (56% identical), IGHV1OR15-9 (56% identical), IGHV7-4-1 (56% identical), and 65 more.
Diseases named in the same sentence as IGHV5-51 in open-access papers:
IGHV5-51 is named in the same sentence as 1 disease in open-access papers, as found by Europe PMC text mining. Sharing a sentence is not in itself a finding about the gene and the disease. The quoted sentences say what the papers report.
dengue (1 paper, 2022). "Moreover, the identification of the IGHV3 antibody gene was consistent with previous reports as it is the most common gene family found in DENV infection, while IGHV5-51 has been described in DENV envelope complex-epitope specific antibodies derived from memory-B cells of dengue patients." (PMID 35617160, 2022).